CD24 (CD24 molecule)
Diseases named in the same sentence as CD24 in open-access papers (continued):
Sharing a sentence is not in itself a finding about the gene and the disease.
tumor (continued). "Analyses of CD44 and CD24 expression showed both cell lines had tumor-initiating CD44+/CD24low cell population, however transformed K5+/K19- cells had more proportion of these cells." (PMID 27941987, 2016). "The expression levels of CD24 were increased in poorly differentiated versus well-differentiated lesions and correlated with tumor grade in a statistically significant manner." (PMID 26978528, 2016). "Cells were sorted from single cell suspensions by flow cytometry based on neu and CD24 expression to separate epithelial and mesenchymal-like cells from the tumor mass." (PMID 27270319, 2016). "CD24 expression correlates with poor patient survival in a variety of human tumor types, and a functional role for CD24 in tumor progression is well established." (PMID 26978528, 2016). "Several studies attribute different functions to CD24 depending on its subcellular localization and it has previously been proposed that intracellular CD24 inhibits tumor cell migration by regulation of BART." (PMID 27203385, 2016). "While all three replicates of non-CD24+CD90+ tumor cells clustered together along the second principle component (22.0%), TIC replicates were more spread, indicating a more heterogeneous population." (PMID 27542270, 2016). "It is particularly worth mentioning that CD24 has been found to be a functional marker to regulate tumor initiation and self-renewal by signal transducer and activator of transcription 3 (STAT3)-mediated Nanog regulation in liver cancer." (PMID 27521216, 2016). "Tumor cells positive for the cell surface markers CD24 and CD90 are known for their high tumorigenicity in the transgenic MMTV-Wnt1 mouse model and have been called cancer stem cells." (PMID 27542270, 2016). "In contrast, no tumor development was observed upon the injection of 100 non-CD24+CD90+ tumor cells." (PMID 27542270, 2016). "SCID mice injected with human MHCC-97 L HCC cells mice together with human CD19+CD24+CD38+ Bregs demonstrated markedly larger tumor growth at 6 weeks and increased serum IL-10 levels compared to SCID mice injected with HCC cells and CD19+CD24−CD38− non-Bregs." (PMID 27437104, 2016). "We have shown, that factors presented in pr.CM increase both the ALDH positivity and expression of CD24−/CD44+/EpCAM+ cell surface markers in tumor cells." (PMID 26759169, 2016). "NDRG2 is a relevant biomarker for predicting aggressive behavior, tumor recurrence and overall patient survival, independently or in combination with other factors, such as CD24, phospho-STAT3, and HOXD1." (PMID 26506239, 2016). "TICs and the far less tumorigenic non-CD24+CD90+ tumor cells of MMTV-PyMT cancers can be distinguished based on their transcriptome profiles and already revealed a specific gene regulation based on their tumorigenic behavior." (PMID 27542270, 2016). "This is demonstrated with the epithelial adhesion molecule E-cadherin, which was strongly reduced in the TIC-derived tumor specimens as well as non-CD24+CD90+ derived tumors." (PMID 27542270, 2016). "Simultaneously, the progression marker CD24 was reduced in infected tumors compared to uninfected controls, demonstrating the reduction of CD24-expressing tumor cells by the OAd virus." (PMID 26824985, 2016). "Conversely, stable transfection of mesenchymal tumor cells with an IKKα-specific shRNA led to an epithelial phenotype and sustained CD24 expression." (PMID 27203385, 2016). "A relatively small retrospective patient tumor analysis suggests that CD24 high tumors go on to show an unfavorable response to cisplatin treatment." (PMID 27276062, 2016). "To address this further, we performed a biochemical measurement of general cysteine cathepsin enzyme activity in TICs and non-CD24+CD90+ tumor cells." (PMID 27542270, 2016). "CD24 knockdown HNSCC lines also generated much smaller tumor burden in the same time period as its vector control lines." (PMID 27276062, 2016).
tumor (continued). "A hypergeometric test using Gene Ontology (GO) Terms shows a general gene upregulation in the categories “developmental process”, “epithelial development”, “cell migration” or “regulation of Wnt signaling” in TICs compared to non-CD24+CD90+ tumor cells." (PMID 27542270, 2016). "IHC confirmed that the expression patterns of the CSC markers were similar in the corresponding tumor tissues, although CD24 and CD44 expression levels were considerably lower." (PMID 27414409, 2016). "Compared with their respective tumor tissues, the cell lines were markedly enriched for CD24+ and CD44+ cells." (PMID 27414409, 2016). "In recent years, CD24 gene has raised considerable interest in tumor biology and poor treatment outcome." (PMID 27276062, 2016). "Although CD24 staining was heterogeneous, significantly fewer invasive well-differentiated tumors expressed CD24 compared to other tumor stages." (PMID 26978528, 2016). "Expression of CD24 in tumor cells correlates with inhibition of metastatic gene signatures, downregulates the mesenchymal transcription factor Twist and upregulates β-catenin expression." (PMID 27203385, 2016). "Strikingly, our study demonstrates that TICs are characterized by a significantly upregulated proteolytic signature compared to the non-CD24+CD90+ tumor cells of this model." (PMID 27542270, 2016). "Consistently, these and other data suggest that CD24 can influence the kinetics of tumor initiation in a context-dependent manner." (PMID 26978528, 2016). "It is intriguing to imagine that surface CD24 “traps” tumor cells in an epithelial phenotype thus inhibiting development to a mesenchymal phenotype, a prerequisite for tumor cell migration." (PMID 27203385, 2016). "CD24 which is involved in cell adhesion and tumor metastasis is expressed not only in PanINs and IPMNs but also in PDAC, which means that like CD133 it does not distinguish between PanINs and IPMNs." (PMID 27332878, 2016). "The number of metastases that developed on the C57BL/6 background in the tumor models used in this current study were too small to detect statistically significant differences between CD24-/- and CD24+/+ mice." (PMID 26978528, 2016). "Our study is the first to show that the proportion of CD44+ and/or CD24+ cells increases in PDAC-derived cell lines compared with the corresponding tumor tissues." (PMID 27414409, 2016). "We provided a new insight into the regulation mechanism of tumor angiogenesis by exploring the role of CD24 in angiogenesis." (PMID 27494878, 2016). "The colony forming efficiency of the CD24+CD90+ tumor cells was 3 fold higher compared to whole tumor cells and 24 times higher compared to non-CD24+CD90+ cells." (PMID 27542270, 2016). "Ultimately, this study addresses the expression of CD24 in human xenografts in nude mice and in human tumor samples to observe any correlation between CD24 levels and the eventual outcome of cisplatin treatment response." (PMID 27276062, 2016). "In line with the mRNA studies this analysis revealed a higher geometric mean value, thus a higher abundance, for Mmp14 at the surface of TICs compared to non-CD24+CD90+ tumor cells." (PMID 27542270, 2016). "CD24 has a variety of biological functions including the regulation of invasiveness and cell proliferation, depending on the tumor entity and subcellular localization." (PMID 27203385, 2016). "In animal studies, Baumann used the flow cytometry method in cancer cells of rat and reported the influence of CD24 in tumor growth (tumor size) and metastasis." (PMID 27099673, 2016). "Although no marker can be used universally to identify cancer stem cells, CD44 and CD24 are used extensively as potential surface markers with which to identify and isolate tumor initiating cells (cancer stem cells) in different cancers." (PMID 25605020, 2015). "In conclusion, our study identifies a potential serologic marker, CD24, for the detection of early CR neoplasia." (PMID 26078485, 2015).
tumor (continued). "Several questions remain to be on the role of CD24 in cancer and more specifically in tumor heterogeneity." (PMID 26040280, 2015). "This analysis suggests that CD24+ cells possess tumor-initiating properties with an advantage to thrive not only at the primary tumor site but also at a distant site by enhanced transendothelial invasion efficiency and matrix remolding at the host tissue." (PMID 26040280, 2015). "In an extended multivariate Cox regression model with inclusion of tumour histology, membranous CD24 expression failed significance, but still showed a trend towards an association with shortened survival times (p = 0.094)." (PMID 26578846, 2015). "Increased expression of the cancer stem cell-associated membrane protein CD24 correlates with tumor aggressiveness; it is also a direct target of HIF-1α and participates in tumor growth and metastasis." (PMID 26056085, 2015). "How CD24 levels in PBLs compare in CR neoplasia and other malignant processes warrants further study." (PMID 26078485, 2015). "These CD24+ cells display highly tumorigenic properties with high metastatic capacity; moreover, these cells can differentiate in vivo, hence creating intra-tumor heterogeneity." (PMID 26040280, 2015). "The low percentage of CD24-high tumours in the TNBC subtype also agrees with the enrichment of CD44+/CD24−/low cells in triple-negative invasive breast cancer." (PMID 26444008, 2015). "We found that hypoxia expands different breast stem/progenitor cell populations (cells with increased aldehyde dehydrogenase activity (Aldefluor+), high mammosphere formation capacity and CD44+CD24−/low cells) both in primary normal epithelial and tumor cells." (PMID 26372732, 2015). "In contrast, low-avidity T cells were shown to upregulate members of the apoptosis pathway (e.g., Bim, FasL, and CD24) promoting their own cell death but also that of other tumor-specific T cells in the tumor microenvironment." (PMID 26635796, 2015). "Ectopic expression of CD24 in tumor cells increases proliferation, promotes tumor cell adhesion to fibronectin, laminin and collagen I, IV (as well as P-selectin), and contributes to greater cell motility and invasiveness." (PMID 26394139, 2015). "As seen in cancer stem cells isolated from tumor xenografts, the 12 T cells showed similar enrichment of surface markers CD24/CD44/ESA and CD133." (PMID 26597727, 2015). "We further document that MM stemness is dependent on CD24, whose knock-down compromises the stem-like properties of the cells including efficient tumour progression." (PMID 25932953, 2015). "Tumours derived from CD24- cells progressed significantly slower than those derived from control (mock-transfected) cells." (PMID 25932953, 2015). "We next tested the effect of CD24 knock-down on the propensity of MM cells to form tumours, such that mock-transfected and CD24- Ist-Mes-2 cells were grafted in NOD/SCID mice and tumour growth kinetics evaluated by USI." (PMID 25932953, 2015). "Terminal tumor weights confirmed these results; both CD24− and CD24+ cells formed significantly larger tumors in the MKR mice (2.6-fold and 1.7-fold, respectively)." (PMID 26040280, 2015). "FACS analysis of the labeled cancer cells revealed that CD24+ cells fuels the cancer process by giving rise to the CD24− cells that comprise the tumor bulk." (PMID 26040280, 2015). "We found that CD44+/ESA+, CD44+/CD24+ cells have a significantly higher possibility for colony and tumor sphere formation than CD44−/ESA− and CD44−/CD24− cells." (PMID 25849939, 2015). "Tumors with high percentage of BCSCs generally have a worse prognosis since as few as 1 × 103 BCSCs can regenerate an entire tumor including both CD24− and CD24+ cells." (PMID 26301220, 2015). "We observed a significant inter-tumoral heterogeneity in the baseline expression of CD44 and CD24, and the distribution was normal between tumours from taxane-treated and taxane-naive patients." (PMID 25669750, 2015).
tumor (continued). "Tumours derived from control cells were highly aggressive and invaded the dorsal abdominal wall, while the smaller CD24- cell-derived tumours were localised subcutaneously." (PMID 25932953, 2015). "We analyzed the clinical data of 139 BIDC cases retrospectively, detecting EGFR, CD44, and CD24 expressions in tumor tissue using immunohistochemistry." (PMID 25429827, 2015). "The rate of tumor growth was significantly less in CD24-positive (p = 0.0003), and CD44-positive (p = 0.0003) tumors compared to the negative populations." (PMID 26449187, 2015). "Patients with CD24-high tumours had significantly shorter patient survival than those with CD24-low tumours." (PMID 26444008, 2015). "This marker is associated with poor prognosis in various tumours and its down-regulation inhibits proliferation and induces apoptosis in tumour cells, whereas increased expression of CD24 promotes tumour growth and metastasis." (PMID 25932953, 2015). "A recent paper by Lee and colleagues documents that CD24 is important for self-renewal of liver TICs and their propensity to form tumours via a complex regulation involving STAT3 and NANOG." (PMID 25932953, 2015). "CD24 was also found to promote tumour cell proliferation and invasion in several types of cancer cells." (PMID 26444008, 2015). "Using human primary PCa xenografts, CD133+ or CD24+ PCa cells, isolated from tumor growths and serially diluted, initiate secondary tumor xenograft formation at comparable frequencies." (PMID 25595909, 2015). "Here, we demonstrate that CD24+ cells create intra-tumor heterogeneity, and display highly metastatic properties." (PMID 26040280, 2015). "Cytoplasmic CD24 staining was observed in 89.5% (85/95) of tumor samples while the positive cases were 71.8% (61/85)." (PMID 26312763, 2015). "There are two possible explanations for the presence of CD24+/CD44+ tumor cells from CD24-/CD44+ tumors." (PMID 24612587, 2014). "IHC staining of xenograft tumor tissues showed positive staining for CD24 on the salivary gland appearing structures." (PMID 24612587, 2014). "Previous studies have shown that the expression of CD24 is correlated with tumor progression and a poor prognosis in various carcinomas." (PMID 25503963, 2014). "Relationships between CD44 and CD24 protein expression levels and tumor parameters were analyzed and their prognostic values were evaluated by Cox proportional hazards models." (PMID 25212506, 2014). "In PDACs, CD24 expression was observed in 87% of cases, with strong or moderate staining on both membrane and cytoplasm of tumor cells." (PMID 25536077, 2014). "Tumor-propagating cells and activity contributed to lung tumor progression and metastasis in CD24-dependent and Yap/Taz-dependent pathways." (PMID 25369529, 2014). "Injection of a small number of CD24+ cells is thus sufficient to induce tumor formation in immunodeficient mice." (PMID 24955581, 2014). "It has been reported that CD24 expression increases the proliferation of tumor cells, induces cell motility and invasion and promotes cell spreading." (PMID 25503963, 2014). "By FACS of fresh tumor biopsies, we isolated the CD44+/CD24- subpopulation from one tumor and ALDH1High cells from a second tumor." (PMID 24998755, 2014). "In the present meta-analysis, we found CD24 expression was related to tumor depth, status of lymph nodes and TNM staging in an expanded sample." (PMID 25503963, 2014). "Compared to the dominant expression of CD24 on the membrane of malignant tumor cells, CD90 was mainly localized in the stroma, including fibroblasts and vascular endothelial cells." (PMID 25536077, 2014). "Seven, eight and six of nine studies investigated the relationship of CD24 expression to invasive depth of tumor, status of lymph node metastasis and TNM stage, respectively." (PMID 25503963, 2014).
tumor (continued). "In this context, CD338 is more stringent and the combination of the two antigens probably results in a better segregation, since the increase of CD338high cells in tumor tissues originated from a CD24+ sorted cell population." (PMID 25216750, 2014). "Quantitative analysis indicated that the numbers of mammospheres from CD44+CD24− CSC were 5- or 9-fold greater than those from CD44+CD24+ and unsorted tumor cells (P < 0.05)." (PMID 25301732, 2014). "As for FACS, tumours were dissociated into single cell suspensions and analysed, sorted and transplanted according to their CD24 and CD29 expression levels." (PMID 24069241, 2013). "The CD44+/CD24−/EpCAM+ population sorted from these lines has stem-like properties and is able to initiate tumour formation much more readily than the luminal population (CD44+/CD24+/EpCam+)." (PMID 23436775, 2013). "Briefly, 13 days after the injection of 1×103 CD44+/CD24-/low cells, a palpable tumor formed in one of six mice." (PMID 23799994, 2013). "Both CD44+ and CD24– have been used as specific markers to identify the BCSCs from human tumor tissues." (PMID 24331293, 2013). "Among them, we were mostly interested in CD24 which is a cancer cell surface marker associated with CRC invasiveness, differentiation, and tumor metastasis." (PMID 23970932, 2013). "Resected tumor tissues from 26 colorectal patients showed significantly lower expression of Pdcd4 and miR-34a, and higher expression of CD24, Src and miR-21 compared to the corresponding normal tissues." (PMID 23533633, 2013). "The in vivo tumor formation assay revealed that CD44+/CD24- cells had the highest tumorigenic capacity compared to the other three subsets." (PMID 23799994, 2013). "The combination of CD44 and CD24 expression have been used to successfully enrich for CSCs in both cell line and tumor samples but caution must be exercised." (PMID 23986719, 2013). "Secondary tumours originated from Lin-CD24hiCD29+ cells fully recapitulated the CD24/CD29 FACS expression profile of the primary lesions." (PMID 24069241, 2013). "As for BC0244 xenograft tumor cells, 83.8% and 54% of IGF1Rhi were CD24--CD44+and ALDH+, respectively, as compared with 48.7% and 31.9% of IGF-1Rlo cells, respectively." (PMID 23663564, 2013). "SWA11, an antibody against CD24 reduced tumor size in xenograft mice transplanted by lung cancer cells A549 and pancreatic cancer cells BxPC3." (PMID 23509802, 2013). "Of the 40 neoplasms with the CD44+/CD24- phenotype described in our study, 37 exhibited histological grades II or III, or were of lymph node metastases." (PMID 24119896, 2013). "They found that the IL-6/JAK2/Stat3 pathway was preferentially active in CD44+ CD24− breast cancer cells compared to other tumor cell types." (PMID 23401782, 2013). "IFN-γ also induced downregulation of CD24 expression such that CD44+CD24- stem-like MMC tumor cells were increased from an average 10% to 55%." (PMID 24324806, 2013). "CD44 is the binding site for hyaluronic acid, and CD24 is a receptor that interacts with P-selectin to induce metastasis and tumor progression." (PMID 23419168, 2013). "In contrast to CD44, L1CAM, and CD97, transplantation of Lin-CD24+CD29+ cells revealed a slight yet significant enrichment in tumour-initiating cells (estimated frequency of 1 in 56463, with CI of 399211 to 7986)." (PMID 24069241, 2013). "Relapsed ANV tumor cells showed characteristics of stem-like cells which included CD44+CD24- phenotype, Sca1 expression, and high rates of tumorigenicity in vivo." (PMID 24324806, 2013). "CD24 is one of the major cell surface glycosylated proteins which function as an adhesive molecules of tumor cells." (PMID 23970932, 2013). "Her2-negative tumor cells had reduced CD24 levels compared with the parental Her2-positive cells and were more mesenchymal in appearance and expression patterns." (PMID 23986719, 2013).